IL15 (interleukin 15)
Diseases named in the same sentence as IL15 in open-access papers (continued):
Sharing a sentence is not in itself a finding about the gene and the disease.
glioma (continued). "IL13Rα2 CAR T cells engineered to additionally express IL-15 displayed greater anti-glioma activity and improved persistence and significantly prolonged survival of mice than control IL13Rα2 CAR T cells in orthotopic glioma xenograft models." (PMID 34113233, 2021). "Consistently, we demonstrated that local administration of IL-15 in tumor mass directly modulates glioma microenvironment, re-boosting the immune response against tumor cells and activating the interaction between NK cells and microglia." (PMID 34552593, 2021). "Transgenic expression of cytokines, such as IL-15, was also demonstrated as a mean to improve anti-glioma activity of CAR-T cells, as shown with IL13Rα2-CAR-T cells." (PMID 33154756, 2020). "Recent data suggested that IL-15 secretable CART and IL13Rα2-CAR.IL15 demonstrated survival advantages in U373 glioma orthotopic xenograft models compared to IL13Rα2-CAR." (PMID 33281826, 2020). "GAMs, stimulated by brain-released BDNF, induced IL-15 production and, consequently, increased NK cells’ infiltration and activation, contributing to limit glioma expansion." (PMID 30123112, 2018). "The BDNF derived from the brain-stimulated microglial cells to produce IL-15 and consequently increase NK cell infiltration and activation, contributing to limit glioma expansion." (PMID 30123112, 2018). "BDNF enriched in glioma environment stimulated the production of IL-15 in CD11b+ macrophages cells and altered macrophage plasticity." (PMID 30034397, 2018). "We have shown that IL13Rα2-CAR T cells have potent antitumor activity in preclinical GBM models, and that expression of secretory (s) IL15 further enhances their anti-glioma activity." (PMID 30400835, 2018). "In microglia sorted from rat C6 gliomas, genes characteristic for M1 activation: Tlr2, Tlr4 and Il18, Cd80, Il12a, Il15 were significantly downregulated." (PMID 29242629, 2017). "The role of IL-15 in modulating the effect of EE was also confirmed with glioma Il15ra–/– mice: in these animals, we observed increased tumor size in SE, and a smaller effect of reducing tumor size in EE." (PMID 29286001, 2017). "(c) Myeloid cell activation (CD68) and infiltration (F4/80) in glioma mass in mice treated with IL-15 or vehicle, as shown in (a), analyzed at the end of treatment (17 days after glioma transplantation)." (PMID 29286001, 2017). "We demonstrate that BDNF stimulated the production of IL-15 in the brain of glioma-bearing mice, and specifically in microglia upon challenge with IL-4 or co-culture with glioma cells." (PMID 29286001, 2017). "In murine GL261-luc gliomas an IL-15 superagonist complex (IL-15N72D:IL-15RαSu-Fc) as a single treatment or in combination with anti-PD-1 antibody, induced a robust anti-tumor immune response resulting in prolonged survival or tumor remission." (PMID 29242629, 2017). "In accordance, chronic infusion of IL-15 increased IFN-γ levels in the brains of glioma-bearing mice." (PMID 29286001, 2017). "We observed that BDNF induced IL-15 production by microglia only upon treatment with IL-4 or co-culture with glioma cells." (PMID 29286001, 2017). "In contrast, when IL-15 is continuously delivered to SE mice with micro-osmotic pumps from day 10 to 17 after glioma transplantation (50 ng ml−1, 100 μl, 0.5 μl h−1), a significant reduction in tumour size is observed." (PMID 25818172, 2015). "We demonstrated that EE mice, in the presence of glioma, have increased mRNA levels of cerebral IL-15, expressed by CD11b+ cells." (PMID 25818172, 2015). "Direct infusion of IL-15 or BDNF in the brain of mice transplanted with glioma significantly reduces tumour growth." (PMID 25818172, 2015). "Furthermore, engineered oncolytic viruses like Ad5-Ki67/IL-15 demonstrate dual functionality: not only eliminating TA-MSCs but also reversing their immunosuppressive effects on glioma cells through PD-L1 downregulation and angiogenesis inhibition." (PMID 40676710, 2025).
glioma (continued). "IL15 is considered a potential therapeutic modulator of immune response in gliomas." (PMID 41009755, 2025). "TM6 might be capable of in vivo transduction of microglia with IL-15 to treat gliomas, but more experimental evidence is required." (PMID 38212785, 2024). "However, in an enriched glioma microenvironment, anti-tumour microglia have a pro-inflammatory phenotype producing increased levels of IL-15 and enhancing the cytotoxicity of proximal natural killer (NK) cells." (PMID 38212785, 2024). "For example, in a Phase 1 study of an EGFRvIII-specific CAR in GBM, a single dose of the CAR-T cells led to downregulation of the EGFR/EGFRvIII receptor, whereas IL13Ra2-specific CAR-T cells co-expressing IL-15 were potent against glioma but led to the rise of tumors with IL13Ra2 downregulation." (PMID 37420216, 2023). "The parallel use of the double-deleted Vaccinia virus (vvDD) or MYXV expressing the IL15Rα-IL15 fusion protein with other combinations such as rapamycin, celecoxib, and specific glioma neoantigen (GARC-1), resulted in a higher efficacy in GL261 murine glioma models." (PMID 36851761, 2023). "Importantly, Ad5-Ki67/IL-15 reduced PD-L1 expression of glioma cells and neovascularization by targeting GA-MSCs." (PMID 35765095, 2022). "Furthermore, the conditioned media from glioma cells treated with Ad5-Ki67/IL-15 significantly inhibited proliferation of GA-MSCs." (PMID 35765095, 2022). "BDNF stimulates the production of Interleukin-15 (IL-15) in the brain of glioma-mice, and IL-15, in turn, stimulates natural kill (NK) cells to produce Interferon-gamma (IFN-γ) that affects the phenotype of myeloid cells, promoting the transition to an anti-tumour state." (PMID 34489641, 2021). "This approach has a high potential for clinical translatability, highlighting the therapeutic efficacy of forced IL-15 production in microglia: the delivery of engineered rAAV2-IL-15 microglia to boost the immune response paves the way to design a new perspective therapy for glioma patients." (PMID 34552593, 2021). "Attempting to reproduce the effect of EE on glioma, we showed that intranasally delivered rAAV2-IL-15 microglia reach glioma and increase NK cell accumulation in glioma-bearing mice, highlighting the fundamental role of IL-15 in the tumor core to boost the immune reaction." (PMID 34552593, 2021). "Moreover, infusion of IL-15 in glioma model mice significantly increases the infiltration of NK cells into tumor and reduces tumor growth." (PMID 34336837, 2021). "In particular, a recent study has demonstrated that glioma-bearing mice exposed to EE showed a reduced tumor size with respect to a standard environment, together with an increase of interleukin 15 (IL-15) and Brain-derived neurotrophic factor (BDNF) intracerebral levels." (PMID 32764487, 2020). "To explore Ad5-Ki67/IL-15’s contribution to augmenting anti-glioma efficacy, we constructed the Ad5-Ki67 using the Ki67 promoter gene instead of the type 5 adenovirus endogenous promoter of the E1A gene, as well as CMV promoter-regulated replication defects adenovirus Ad5-GFP (1 × 1012 vp/ml)." (PMID 33133514, 2020). "Compared with IL-15, collective evidence for relevance of IL-16 to glioma aetiology is limited." (PMID 30297770, 2018). "We demonstrated that, in glioma-bearing mice, brain infusion of IL-15: i) increased the frequency of infiltrating NK cells in the ILH, ii) increased the frequency of NK cells producing IFN-γ, and iii) mimicked the effect of EE on the switch to an inflammatory gene expression in myeloid cells." (PMID 29286001, 2017). "We focused our attention on the role played by IL-15 in the brain of EE glioma-bearing mice." (PMID 25818172, 2015). "All together, these data prompt to consider IL-15 as the possible therapeutic target in glioma." (PMID 25818172, 2015).
glioma (continued). "We demonstrate that the reduction in glioma size in EE-housed mice is mediated by an increase in brain IL-15, which favours NK cell accumulation and antitumour function, and BDNF, which suppresses M/Mφ infiltration and activity, and directly affects tumour cell migration." (PMID 25818172, 2015). "IL-15 expression has been documented to increase following oHSV administration to glioma-bearing mice and rats, and may contribute to restricting oHSV replication and thus efficacy." (PMID 24312353, 2013). "In addition, we found Ad5-Ki67/IL-15 could attenuate PD-L1 expression of mouse glioma cells induced by GA-MSCs in GBM treatment (P < 0.05, 46.03 ± 6.793 vs. 35.37 ± 0.666)." (PMID 35765095, 2022). "To determine whether the recombinant viruses expressed physiologically relevant levels of IL-15, we quantified culture supernatants from Ad5-Ki67/IL-15-treated GL261, U251, and U87 glioma cells and primary cells BT-01 cells using a commercially available ELISA kit specific for IL-15 heterodimers." (PMID 33133514, 2020). "However, motor activity is only one of the aspects potentiated in EE and it is not known whether more prolonged exercise, similar to that offered to mice in our experimental protocol, is sufficient to increase cerebral IL-15 in glioma-bearing mice." (PMID 25818172, 2015). "We report that EE exposure affects: (i) tumour size, increasing mice survival; (ii) glioma establishment, proliferation and invasion; (iii) microglia/macrophage (M/Mφ) activation; (iv) natural killer (NK) cell infiltration and activation; and (v) cerebral levels of IL-15 and BDNF." (PMID 25818172, 2015). "For instance, in a preclinical study targeting IL13Rα2-positive gliomas, the expression of IL-15 significantly extended the survival of IL13Rα2-CAR T cells and improved their efficacy against gliomas." (PMID 39506843, 2024). "Currently, clinical trials combining IL-15 with CAR-T therapy have been initiated in hematological malignancies; however, in the context of glioma treatment, it remains at the preclinical stage, and its clinical efficacy has yet to be validated." (PMID 39506843, 2024). "They observed the strong reactivity of T cells using IL-2/IL-15/IL-2, given by the production of IFN-γ in the blood of patients with grade III glioma compared to patients with grade II glioma." (PMID 37759505, 2023). "We recently reported that microglial production of IL-15, in glioma bearing in EE-housed mice, recruits IFN-γ+ NK cells, with effects on glioma growth." (PMID 34552593, 2021). "We reported that mice that received rAAV2-IL-15 microglia had a higher number of IL-15/IBA1 double-positive cells in the tumor area, 17 days after glioma transplantation." (PMID 34552593, 2021). "To explore IL-15-mediated anti-glioma immunity, we treated HMC3 and BV2 microglia cells using Ad5-GFP, Ad5-Ki67/GFP and Ad5-Ki67/IL-15." (PMID 33133514, 2020). "We found that IL-15 levels were higher in the GL261, U251 and U87 glioma cells and primary cells BT-01 treated with Ad5-Ki67/IL-15 than in the control group after 24, 48, 72, and 96 h." (PMID 33133514, 2020). "In this regard, IL-13Rα2-CAR T cells modified to secrete IL-15 (IL-13Rα2.IL-15-CAR) demonstrated superior proliferative capacity and antitumor activity in vitro and in vivo against high grade glioma compared to IL-13Rα2-CAR alone." (PMID 30828333, 2019). "In a glioma model, an IL13Rα2 specific CAR T cell that also had transgenic expression of IL-15 successfully killed tumor, proliferated, and produced cytokine in vivo; however, recurrent tumors demonstrated IL13Rα2 downregulation." (PMID 30804938, 2019). "Once NK cells are activated by various means including IL-2, IL-15, or PHA, they can overcome immune escape of glioma, such as HLA class I molecules, by overwhelming the activating signals." (PMID 28203118, 2017). "We investigated the possible effects of BDNF on glioma biology, demonstrating that the infusion of BDNF in mouse brain induces IL-15 production by CD11b+ cells." (PMID 29286001, 2017).
glioma (continued). "This research is innovative because the therapeutic efficacy of a dual-regulated OAd armed with IL-15 for glioma has not been designed or tested to date." (PMID 33133514, 2020). "While IL-15 produced by CD11b+ cells modulates NK cell infiltration and antitumour activity, BDNF reduces M/Mφ infiltration and the invasion of cerebral parenchyma by glioma cells through Trkb.T1, both contributing to limit glioma expansion." (PMID 25818172, 2015). "Interleukin-15 (IL-15) and BDNF are two key mediators of these effects, since they increase in the brain of EE mice, and their in situ administration reduces tumour size in glioma-bearing mice, similarly to EE." (PMID 25818172, 2015). "Notably, MDSCs in the glioma TME express the IL-15 receptor, CAR-T cells engineered to express IL-15 create a dual-targeting system that reduces the presence of both MDSCs and glioma cells while reversing the immunosuppressive effects of MDSCs in laboratory settings." (PMID 41368628, 2025). "In vivo, oncolytic HSV-1 OV-IL15C, expressing human IL-15 and its receptor IL-15Rα, were demonstrated to have significant suppression of tumor growth and prolonged survival in glioma-bearing mice compared to a therapy using the same OV without IL-15/IL-15Rα gene insertion." (PMID 38396720, 2024). "Furthermore, Ad5-Ki67/IL-15 can reduce GA-MSC-mediated PD-L1 expression and angiogenesis in glioma." (PMID 35765095, 2022). "However, the therapeutic efficacy of IL-15 in glioma has not been tested until recently, partially due to its short half-life and low biological activity in vivo, and the systemic, non-local route of administration." (PMID 34552593, 2021). "We reported previously previously that a cytokine cocktail comprising IL-2, IL-15 and IL-21 selectively increases the population of central/effector memory tumor-reactive tumor-infiltrating lymphocytes (TIL) from pancreatic cancer as well as TIL from WHO grade 4 glioma after ex vivo expansion." (PMID 29854291, 2018). "Control experiments confirmed that glioma cells were not the source of IL-15." (PMID 29286001, 2017). "Importantly, we also demonstrate a direct link between IL-15 production and NK cell antitumour activity since IL-15 infusion does not inhibit glioma growth in NK cell-depleted mice." (PMID 25818172, 2015). "We observed that VEGF levels in the Ad5-CM, Ad5-Ki67-CM and Ad5-Ki67/IL15-CM treated groups from GL261, U251, and U87 glioma cells and primary cells BT-01 were significantly decreased, indicating that OAd may inhibit angiogenesis by attenuating VEGF secretion from glioma cells." (PMID 33133514, 2020). "Interestingly, the IL-15-dependent modulation of gene expression was completely absent in glioma-bearing mice in which NK cells were depleted, further supporting the hypothesis that IL-15 modulates CD11b+ cell phenotype by acting through NK cells." (PMID 29286001, 2017). "Interestingly, we never detect increase of IL-15 in EE mice in the absence of glioma, suggesting the requirement of at least two different initiating signals, one from glioma-conditioned microenvironment and one from factor(s) produced in the brain on EE housing." (PMID 25818172, 2015).
ovarian carcinoma (39 papers, 2010 to 2026). A malignant neoplasm originating from the surface ovarian epithelium. "Higher percentages, function, and IL-15-mediated activation of ascites-derived NK cells were found to be associated with a better prognosis in ovarian cancer patients." (PMID 38932405, 2024). "In an ovarian cancer mouse model, expanded natural killer (eNK) cells were delivered once weekly and interleukin-15 (IL-15) thrice weekly." (PMID 41937949, 2026). "Ex vivo activation of NK cells with cytokines like IL-2, IL-12, IL-15, or IL-18 enhances proliferation, cytokine secretion, and the ability to lyse ovarian cancer cell lines, even those with low MHC-I expression." (PMID 41375063, 2025). "Another advancement was the creation of anti-mesothelin CAR Vδ2 T cells, which showed effective targeting of ovarian cancer both in vitro and in vivo, with increased IL-15 expression further enhancing anti-tumor effects." (PMID 40148988, 2025). "Trophoblast cell-surface antigen 2 (TROP2)-CAR-NK cells engineered with IL-15 and delivered intraperitoneally are under study for platinum-resistant ovarian cancer (ClinicalTrials.gov identifier: NCT05922930)." (PMID 41375063, 2025). "In ovarian cancer, NK cells stimulated with IL-12, IL-15, and IL-18, known as CIML NK cells, have shown promising clinical trial results." (PMID 41375063, 2025). "The IL-15 super-agonist complex was found to up-regulate NK cell-mediated cytotoxicity against ovarian cancer cell lines in both in vitro and in vivo studies." (PMID 38932405, 2024). "A large number of cytokines have been reported as elevated in ovarian cancer ascites samples including IL-6, IL-8, IL-10, IL-15, IP-10/CXCL10, MCP-1/CCL2, Mip1α/CCL3, Mip1β/CCL4, MDC, and VEGF." (PMID 36860657, 2023). "Effector memory CD8 T cells have been reported to play a role in IL-15 signaling-related antitumor activity of PD-1 inhibitors, as well as prognosis prediction of gastric cancer, lung cancer and ovarian cancer." (PMID 35734185, 2022). "A recombinant VACV expressing a superagonist IL-15 (a fusion protein of IL-15 and IL-15Rα) led to significant tumor regression and extended survival of the mice bearing colon or ovarian cancer." (PMID 36146629, 2022). "For example, the use of IL-15 can enhance NK cell cytotoxic function against ovarian cancer and IL-27 has been shown to enhance IL-15 mediated NK cell activation." (PMID 31681561, 2019). "In this regard, it has been reported that adaptive NK cells induced by different cytokines (IL-12, IL-15, IL-18) display both in vitro and in vivo enhanced functionality and persistence against ovarian cancer." (PMID 30791364, 2019). "In search for a more powerful vaccine, we compared the efficacies of IL-15 DCs and IL-4 DCs in the context of a metastatic murine ovarian cancer model." (PMID 30621204, 2019). "Upon exposure to either inflammatory factors including IFNα, IL-15, IL-12 and IL-2, or ovarian cancer cells, NK cells primed by IL-18 can release chemokines CCL3 and CCL4 to attract immature dendritic cells (iDCs)." (PMID 28929459, 2018). "In our mouse model of ovarian cancer, tumor regression was entirely dependent on IL-2/IL-15 signaling." (PMID 21203522, 2010). "On the other hand, NK cells are known to be increased in the tumor microenvironment in ovarian cancer and have early cytolytic activity on cancer cells, and several therapies have been tested in clinical trials to recruit NK cells in ovarian cancer using IL-15 and IL-2 with limited success." (PMID 40806640, 2025). "Another promising yet challenging area of immunotherapy in ovarian cancer is cytokine therapy, which aims to enhance the immune response by administering or modifying specific cytokines, such as IL-2, IL-12 and IL-15, that activate natural killer (NK) and cytotoxic T lymphocytes." (PMID 40722601, 2025).